ZNF345 (zinc finger protein 345)
Description:
May be involved in transcriptional regulation.
Synonyms: HZF10
Tractability: No criterion of Open Targets' tractability assessment is met for any kind of drug.
Gene: Protein-coding gene on chromosome 19 (36,850,338 to 36,913,029, forward strand). Ensembl gene ENSG00000251247.
Subcellular location: Nucleus
Gene Ontology:
Molecular function: protein binding; sequence-specific double-stranded DNA binding; DNA-binding transcription activator activity, RNA polymerase II-specific; RNA polymerase II cis-regulatory region sequence-specific DNA binding
Biological process: negative regulation of transcription by RNA polymerase II; regulation of transcription by RNA polymerase II; regulation of transcription by RNA polymerase III; transcription by RNA polymerase II; transcription by RNA polymerase III; positive regulation of transcription by RNA polymerase II
Cellular component: nucleus
Genetic constraint (gnomAD): Loss-of-function variants: 4 observed, 0.96 expected, observed/expected ratio (o/e) 4.17. That is too few expected variants to judge how well the gene tolerates losing a copy. Missense variants: 527 observed, 619.83 expected, observed/expected ratio (o/e) 0.85, 90% interval 0.79 to 0.91. Synonymous variants: 166 observed, 197.67 expected, observed/expected ratio (o/e) 0.84, 90% interval 0.74 to 0.95.
Homologues: Orthologues: macaque ZNF345 (98% identical), rat Zfp11 (54% identical), mouse Zfp11 (53% identical). Paralogues in human: ZNF790 (32% identical), ZNF383 (27% identical), ZNF268 (27% identical), ZNF7 (27% identical), ZNF283 (26% identical), ZNF30 (26% identical), ZNF471 (26% identical), ZNF546 (26% identical), ZNF708 (26% identical), ZFP2 (26% identical), ZNF492 (26% identical), ZNF33B (25% identical), and 164 more.
Diseases named in the same sentence as ZNF345 in open-access papers:
ZNF345 is named in the same sentence as 3 diseases in open-access papers, as found by Europe PMC text mining. Sharing a sentence is not in itself a finding about the gene and the disease. The quoted sentences say what the papers report.
Barrett’s oesophagus (1 paper, 2018). "TFPI2, TWIST1, ZNF345 and ZNF569 methylation have promise as diagnostic biomarkers for Barrett’s oesophagus when used in combination with a simple and cost effective non-endoscopic cell collection device." (PMID 29084829, 2018).
cancer (1 paper, 2018). A tumor composed of atypical neoplastic, often pleomorphic cells that invade other tissues. "ZNF345 and ZNF569 are novel methylation markers that have not previously been reported to be hypermethylated in cancer." (PMID 29084829, 2018).
ZNF345 also shares sentences with these, for which no sentence is quoted: pancreatic cancer (1 paper).